APOE (apolipoprotein E)
Diseases named in the same sentence as APOE in open-access papers (continued):
Sharing a sentence is not in itself a finding about the gene and the disease.
atherosclerosis (continued). "For example, LPS caused wide-spread vascular inflammatory responses, and worked as an aggravating factor in mouse apoE-deficient atherosclerosis." (PMID 27167346, 2016). "In aged mouse skeletal muscle, miR-434-3p levels were found to be decreased and in ApoE-deficient mice during the disease progression of atherosclerosis." (PMID 27153060, 2016). "ATLOs have been identified in aged atherosclerosis-prone hyperlipidemic apolipoprotein E-deficient (ApoE−/−) mice: they are organized into distinct immune cell compartments, including separate T-cell areas, activated B-cell follicles, and plasma cell niches." (PMID 27777573, 2016). "In previous studies using p27Kip1 or ApoE-deficient mice, p27Kip1 expression was reported to be an important factor in preventing atherosclerosis." (PMID 27465365, 2016). "Several genetic risk markers for immune-metabolic diseases such as atherosclerosis, including apoE, are associated with pathogen recognition or inflammatory pathways." (PMID 27383250, 2016). "In ApoE−/− mice, Ccl17 deficiency entailed a reduction of atherosclerosis, which was dependent on T-regulatory cells." (PMID 27491335, 2016). "This study shows that hypoxanthine induces cholesterol accumulation in hepatic cells through alterations in the enzymes that control lipid transport and the development of atherosclerosis in APOE‐deficient cells and mice." (PMID 27396856, 2016). "Effects of BM-573 were measured on endothelial vasodilatory function, NO bioavailability, oxidative stress in resistance vessels from apolipoprotein E-deficient (ApoE-KO) mice at early stages of atherosclerosis." (PMID 27019366, 2016). "It is possible that CD36 is critical for the development of arthritis in our model similar to its role in atherosclerosis where loss of CD36 improves atherosclerosis in ApoE−/− mice by over 60 %." (PMID 27287704, 2016). "The atherosclerosis is stable on WD and the GK+/−ApoE−/− knockout shows comparable coronary vascular function to the apolipoprotein E (ApoE) deficient mice at 18 weeks of age." (PMID 27774459, 2016). "An atherosclerosis model was established by placing a perivascular collar on the right common carotid artery in apolipoprotein E-deficient (ApoE-/-) mice." (PMID 27846838, 2016). "There are reports that apolipoprotein E deficient mice (apoE) fed with high-cholesterol diet develop severe atherosclerosis compared to apoE and cyclophilin A-deficient mice, indicating that cyclophilin A deficiency in vivo decreases atherosclerotic lesions." (PMID 27809851, 2016). "Both Bmal1−/−Apoe−/− and L-Bmal1−/−Apoe−/− mice showed increased hyperlipidaemia and atherosclerosis compared with apoE-deficient mice." (PMID 27721414, 2016). "In contemporary research on atherosclerosis, the most extensively characterized strains are those deficient in apolipoprotein E (ApoE−/−) and low-density lipoprotein (LDL−/−) receptors." (PMID 27618031, 2016). "ApoE-deficient mice and also, to a lesser extent, human ApoE4 knock-in mice display a pro-atherogenic lipoprotein profile leading to atherosclerosis." (PMID 27171180, 2016). "Previous work from our laboratory showed that in the ApoE*3 Leiden mouse, a transgenic rodent which has a predisposition to atherosclerosis, maternal protein restriction during fetal development increased atherosclerotic lesion size in adult life." (PMID 27777632, 2016). "Loss of TLR9 function thus exacerbates atherosclerosis in ApoE null mice exposed to a high fat diet." (PMID 27795867, 2016). "This study identified systemic changes of specific plasma metabolites that are associated with the progression of atherosclerosis in ApoE−/− mice." (PMID 27721472, 2016). "We have previously shown that ApoE-/-Dgat1-/- mice are protected from developing atherosclerosis in association with reduced foam cell formation." (PMID 27223895, 2016).
atherosclerosis (continued). "In conclusion, removal of ADAMTS4 in ApoE-deficient mice reduces atherosclerosis and enhances plaque stability." (PMID 27491335, 2016). "In another study, ApoE−/− (Apolipoprotein E)-deficient mice fed on high fat diet and infected with Chlamydia resulted in accelerated atherosclerosis with a presence of activated myeloid DCs (mDCs) and plasmacytoid DCs (pDCs)." (PMID 27994587, 2016). "The understanding of this process has been facilitated by the use of ApoE knockout mice since functional mutations in ApoE lead to elevations in serum cholesterol levels and premature atherosclerosis in both mice and humans." (PMID 27287704, 2016). "Genetic deficiency of TLR2 reduces diet-induced atherosclerosis in ApoE+/− mice, and TLR2 expression and activation regulates the inflammatory processes and ROS production following vascular injury in mouse models." (PMID 27795867, 2016). "DNA methylation induced foam cell formation from macrophages and promoted atherosclerosis in apolipoprotein E-deficient (apoE−/−) mice." (PMID 27295295, 2016). "We used two animal models, ApoE-deficient mice and a carotid partial ligation model, to study the effect of irisin in atherosclerosis and neointima formation." (PMID 27355581, 2016). "In mice deficient of apolipoprotein E (Apoe-/-), aspirin (20, 50 mg/kg/day) suppressed the progression of atherosclerosis in aortic roots and increased the plaque stability in carotid atherosclerotic plaques induced by collar-placement." (PMID 27391154, 2016). "In this study, the effect of DHT on atherosclerosis were investigated using apolipoprotein E-deficient (ApoE-/-) mice and endothelial cells." (PMID 27891092, 2016). "The in vivo effect of omentin-1 halted the development of atherosclerosis has been investigated in apolipoprotein E-deficient (Apoe−/−) mice with decreased macrophage infiltration and pro-inflammatory genes expression." (PMID 27352781, 2016). "The ApoE knockoutmouse is more suitable for presenting a deficiency in the gene encoding ApoE and forbeing predisposed to hypercholesterolemia inducing atherosclerosis." (PMID 27759775, 2016). "In the pursuit of a rapid and representative atherosclerosis model, perivascular collar placement and a high-fat diet in ApoE-deficient (ApoE-/-) mice has been used in several studies." (PMID 27846838, 2016). "ApoE−/− mice deficient in TLR4 have reduced atherosclerosis, which establishes that TLR activated pathways contribute to disease development." (PMID 27166190, 2016). "In this work, we investigated the role of ADAMTS4 in diet induced atherosclerosis using apolipoprotein E deficient (ApoE−/−) and Adamts4 knockout mice." (PMID 27491335, 2016). "Our results demonstrate that loss of ADAMTS4 attenuated diet induced atherosclerosis with significantly reduced plaque burden in ApoE-deficient mice." (PMID 27491335, 2016). "Atherosclerosis-prone ApoE−/− mice with deficiency of TLR4 or MyD88 show attenuation in atherosclerosis development through decreased macrophage recruitment." (PMID 27795867, 2016). "Apolipoprotein E (ApoE) is implicated in clearance of triglycerides from the serum and ApoE deficient (ApoE−/−) mice develop marked hyperlipidemia and are widely used as a model of atherosclerosis." (PMID 26814757, 2016). "Hypoxanthine induces cholesterol accumulation in hepatic cells through alterations in enzymes that control lipid transport and induces atherosclerosis in APOE‐deficient cells and mice." (PMID 27396856, 2016). "VEGF-A, the major VEGF subtype, is detected at all stages of human coronary atherosclerosis and promotes atherosclerosis progression in apoE/apoB100 double-deficient mice and rabbits." (PMID 26908443, 2016).
atherosclerosis (continued). "To explore the contribution of low-grade inflammation to the development of atherosclerosis, we first tested the effect of subclinical super-low-dose LPS on the pathogenesis of atherosclerosis in the Apolipoprotein E-deficient animal model." (PMID 27824038, 2016). "The observation that paraoxonase 2-deficient apoE−/− mice develop enhanced mitochondrial oxidative stress and exacerbated atherosclerosis supports the evidence for a role of disturbed PON activity in vascular injury." (PMID 28058087, 2016). "In line, Kannisto and co-workers recently showed that GC-1 is able to reduce atherosclerosis, defined as cholesterol content in the arterial wall, in aortas of ApoE-deficient mice." (PMID 26886134, 2016). "Atherosclerosis-prone apolipoprotein E-deficient (Apoe−/−) mice display poor lipoprotein clearance with subsequent accumulation of cholesterol ester-enriched particles in the blood, which promote the development of atherosclerotic plaques." (PMID 27207171, 2016). "Prenatal iAs exposure is also associated with accelerated/exacerbated atherosclerosis in apolipoprotein A-knockout (ApoE–/–) mice, a mouse strain used to study atherosclerotic disease." (PMID 26115410, 2016). "In this study, we investigated the role of hypoxanthine on cholesterol synthesis and atherosclerosis development, particularly in apolipoprotein E (APOE)‐deficient mice." (PMID 27396856, 2016). "Cryptotanshinone showed protective effects on atherosclerosis of ApoE-deficient mice and can improve the situation caused by apolipoprotein shortage, which also was able to inhibit expression of oxidized adhesion molecules induced by LDL." (PMID 27366196, 2016). "In ApoE‐deficient mice, macrophage‐specific deletion of SR‐BI resulted in advanced atherosclerosis, with an 86% increase in average lesion area." (PMID 26493158, 2016). "The present study tested the feasibility of delivering miR-146a/-181b by affinity targeting to E-selectin and its effectiveness for the reduction of endothelial inflammation and atherosclerosis in apolipoprotein E-deficient (ApoE−/−) mice." (PMID 26956647, 2016). "When a tapered cast was placed around the carotid artery in ApoE-deficient mice, low NO production and advanced lesions were observed in the atherosclerosis-prone flow separation region located immediately downstream of the cast." (PMID 26221589, 2015). "To determine the physiologic androgen receptor (AR)–dependent actions of androgens on atherogenesis in female mice, we generated female AR-knockout (ARKO) mice on an atherosclerosis-prone apolipoprotein E (apoE)–deficient background." (PMID 25550469, 2015). "Inhibition of the LPA-mediated CXCL1 release impairs monocyte adhesion and atherosclerosis in apolipoprotein E-deficient mice." (PMID 26001902, 2015). "For example, we reported that 4-MU treatment was associated with worse atherosclerosis in ApoE-deficient mice fed a high-fat diet." (PMID 25852691, 2015). "More specifically, a 5% (w/w) SPH diet reduced atherosclerosis in apoE−/− mice and attenuate risk factors related to atherosclerotic disorders by acting both at vascular and systemic levels and not directly related to changes in plasma lipids or fatty acids." (PMID 25949827, 2015). "Apolipoprotein E-deficient (ApoE−/−) mouse is the most popular animal model used in the study of atherosclerosis." (PMID 25874925, 2015). "To explore the ability of αvβ3 integrin-targeted probes to detect atherosclerotic lesions with a high risk of rupture, we established mouse models of atherosclerosis by feeding a high-cholesterol diet to apoE-deficient (ApoE-/-) mice." (PMID 26123253, 2015). "For example, 4-MU treatment was also associated with worse atherosclerosis in ApoE-deficient mice fed a high-fat diet." (PMID 25852691, 2015).
atherosclerosis (continued). "The proatherogenic role of M-CSF and its receptor was shown in apolipoprotein E (ApoE)-deficient mice, a murine strain susceptible to atherosclerosis." (PMID 25973901, 2015). "Mice deficient in apoE develop severe atherosclerosis on a 4.5% fat-containing diet, become a powerful tool in atherosclerosis research." (PMID 25661015, 2015). "We therefore investigated the effects of a chronic internal exposure to 137Cs on atherosclerosis in predisposed ApoE-/- mice." (PMID 26046630, 2015). "Herein we evaluated the feasibility of SPECT/CT imaging using 99mTc-IDA-D-[c(RGDfK)]2 to noninvasively detect high-risk plaques in established mouse models of atherosclerosis by feeding a high-cholesterol diet to ApoE-/- mice." (PMID 26123253, 2015). "In apolipoprotein E-deficient (Apoe−/−) mice, chronic treatments with endostatin reduced intimal neovascularization and inhibited plaque growth by 85% in atherosclerosis." (PMID 26006236, 2015). "Our data indicated that TLR9 inactivation ameliorated atherosclerosis via skewing macrophage plasticity to M2 phenotype in ApoE-deficient mice." (PMID 26257462, 2015). "Mice with an homozygous Apolipoprotein E gene depletion (ApoE KO) are also predisposed to elastic fiber fragmentation as well as to atherosclerosis and atherosclerotic plaque formation." (PMID 25883602, 2015). "Previous work demonstrated that the systemic administration of recombinant IL‐33 reduces the development of atherosclerosis in apolipoprotein E‐deficient (ApoE−/−) mice by inducing a Th1‐to‐Th2 shift." (PMID 26417439, 2015). "Transgenic over-expression of BMP-2 under the direction of the SMA promoter accelerated intimal calcification in ApoE-deficient mice with atherosclerosis." (PMID 25603410, 2015). "In animal model of apolipoprotein-E-deficient (-/-) mice, immunizations with P. gingivalis enhanced atherosclerosis." (PMID 26114433, 2015). "Recently, disruption of ANGPTL2 in apolipoprotein E-deficient mice (ApoE-/-/Angptl2-/-) was found to attenuate atherosclerosis progression by decreasing the number of macrophage infiltrating atheromatous plaques, thereby reducing vascular inflammation." (PMID 25889082, 2015). "This is based on the genetic associations between APOE variants and many age-related diseases, such as coronary heart disease, atherosclerosis, age-related macular degeneration (AMD), and Alzheimer's disease." (PMID 25476875, 2015). "Disruption of miRNA biogenesis in ECs by endothelial Dicer deletion reduced the expression of CXCL1 in the arteries of apolipoprotein E-deficient mice, thereby attenuating monocyte adhesion to early atherosclerosis-prone endothelium." (PMID 26001902, 2015). "In the present work, we assessed the effects of lentivirus-mediated MEF 2A shRNA on the progression of atherosclerotic plaque and associated inflammatory process following collar-induced atherosclerosis in APOE KO mice." (PMID 25793529, 2015). "Loss of ApoE expression in hematopoietic cells appears to drive monocyte proliferation, mobilization, and differentiation in the development of atherosclerosis." (PMID 25852821, 2015). "Genetic ACE2 deficiency accentuates vascular inflammation and atherosclerosis in the apolipoprotein E (ApoE) knockout (KO) mouse with larger vascular lesions in aortic atherosclerotic plaques." (PMID 26245758, 2015). "STZ-induced diabetic apoE−/− model has previously been confirmed as feasible for the study of diabetes-associated atherosclerosis by the Animal Models of Diabetic Complications Consonium (AMDCC) 28 and some previous studies." (PMID 25661015, 2015).
atherosclerosis (continued). "For example, human SNP rs2075650 in Chr 19 has been associated with increased CAD risk and is near the APOE/APOC1 genes whose roles in atherosclerosis are well established." (PMID 26694027, 2015). "The deletion of genes encoding M-CSF and its receptor led to significantly diminished atherosclerosis in ApoE-deficient mice 12,13." (PMID 25973901, 2015). "An atherosclerosis model was induced by in vivo perivascular constrictive silica collar placement on the left common carotid arteries in male apolipoprotein E-deficient (ApoE−/−) mice." (PMID 25395016, 2015). "Of note, the administration of recombinant IL‐33 exerted a protective effect in the apolipoprotein E‐deficient (ApoE‐/‐) mouse model of atherosclerosis." (PMID 26417439, 2015). "In this study, we examined the impact of hepatic MsrA overexpression on lipid metabolism and atherosclerosis in apoE-deficient (apoE−/−) mice." (PMID 26318157, 2015). "Atherosclerosis-prone apoE deficient mice were administrated IL-25 during both early (10–14 weeks of age) and late (21–25 weeks of age) stages of atherosclerosis to evaluate if IL-25 have any influence on the plaque initiation or plaque progression." (PMID 25629516, 2015). "Apolipoprotein E- (ApoE-) deficient mice spontaneously develop atherosclerosis when fed on high cholesterol diet." (PMID 26221589, 2015). "Regarding the aggravation of atherosclerosis by IH in ApoE-deficient mice, we recently demonstrated that this deleterious effect involved inflammatory alterations of EWAT, as EWAT lipectomy prevented the proatherogenic effect of IH." (PMID 25873766, 2015). "We have previously demonstrated that exercise training prevents the development of Angiotensin (Ang) II-induced atherosclerosis and vulnerable plaques in Apolipoprotein E-deficient (ApoE-/-) mice." (PMID 26600018, 2015). "The designed workflow took advantage of the well-established methodology to isolate DRM microdomains from lung tissue of ApoE deficient mice to investigate the molecular mechanisms specifically modified in atherosclerosis." (PMID 26628893, 2015). "The mouse apolipoprotein E–deficient (ApoE−/−) model of atherosclerosis has been used extensively to investigate human CVD." (PMID 26200752, 2015). "Here we report the effect of Pak1 on atherogenesis using atherosclerosis-prone apolipoprotein E-deficient (ApoE−/−) mice as a model." (PMID 26104863, 2015). "Further, miR-155 deficiency in Apolipoprotein E knockout (ApoE-KO) mice attenuated atherosclerosis by reducing macrophage inflammation and Th17 cell numbers." (PMID 26783845, 2015). "Pulmonary instillation of TiO2 NPs results into plaque progression in atherosclerosis-prone apolipoprotein E-deficient (apoE−/−) mice." (PMID 25803285, 2015). "A study demonstrated that deficiency of APN in ApoE−/− mice promotes atherosclerosis and T-lymphocyte accumulation in the atherosclerotic lesions." (PMID 26020520, 2015). "ApoE−/− mice have a high risk of developing lipid metabolism disorders and have been reported to rapidly develop hyperlipidemia and atherosclerosis." (PMID 26080706, 2015). "The technique was shown to be suitable for quantifying lesion size in three commonly used models: (i) femoral artery wire-injury; (ii) femoral artery ligation, and (iii) diet-induced atherosclerosis in apolipoprotein E deficient (apoE-/-) mice." (PMID 26067588, 2015). "Mice with a heterozygous deletion of perlecan exhibited a partially reduced expression of perlecan in the arterial wall and the deletion resulted in less atherosclerosis in young ApoE-deficient mice." (PMID 25528754, 2015).